EGFR (epidermal growth factor receptor)
Diseases named in the same sentence as EGFR in open-access papers (continued):
Sharing a sentence is not in itself a finding about the gene and the disease.
breast carcinoma (continued). "Ivermectin binds to the extracellular domain of EGFR, inhibiting the activation of EGFR and its downstream signaling cascade ERK/Akt/NF-κB, thereby enhancing the antitumor efficacy of doxorubicin against breast cancer cells." (PMID 39881881, 2024). "Neratinib, a small-molecule tyrosine kinase inhibitor (TKI) that irreversibly binds to human epidermal growth factor receptors 1, 2 and 4 (HER1/2/4), is an approved extended adjuvant therapy for patients with HER2-amplified or -overexpressed (HER2-positive) breast cancers." (PMID 39002022, 2024). "EGFR over-expression, correlation between EGFR-HER3 axis activation and poor outcome, and higher levels of cytoplasmic Src in TNBC compared to other breast cancer subtypes also point to potential therapeutic value for a pan-HER inhibitor and Src inhibitor in TNBC." (PMID 39191139, 2024). "In addition, by preventing estradiol from upregulating bcl-2, c-myc, and EGFR, SHBG is conducive to the recovery of the apoptosis mechanism of breast cancer cells." (PMID 38465341, 2024). "CXCL12 was shown to transactivate HER2-neu in the breast cancer cell lines MDA-MB-361 and SKBR3, which express both CXCR4 and HER2-neu that was inhibited by AMD3100, a CXCR4 inhibitor, PKI 166, an epidermal growth factor receptor/HER2- tyrosine kinase inhibitor, and PP2, a Src kinase inhibitor." (PMID 39001456, 2024). "Glabridin activates the apoptosis pathway by upregulating caspases 3, 8, and 9 to reduce cell viability; it inhibits phosphorylated EGFR, and p-AKT, blocking breast cancer proliferation signals; and lowers intracellular ROS levels, reducing oxidative stress and inhibiting tumor progression." (PMID 39723390, 2024). "Of the chosen gene signatures, MYO1D has been found to have increased expression levels in breast cancer and has the capacity to upregulate the expression of the Epidermal Growth Factor Receptor (EGFR), which improves the motility and viability of colorectal and breast cancer cells." (PMID 38512527, 2024). "Although there was literature reported EGFR as a potential therapeutic target in TNBC, to date, there is still insufficient clinical trial evidence demonstrating significant efficacy of Gefitinib in breast cancer treatment." (PMID 38751445, 2024). "Furthermore, a study examining the expression of epidermal growth factor receptor (EGFR) and the cell surface protein CD133 in CTCs of breast cancer patients found a significant link between positive EGFR expression in CTCs and luminal-type tumors." (PMID 38256428, 2024). "This hypothesis was confirmed in our study, which revealed a significant decrease in the levels of phosphorylated EGFR, PI3K, AKT, and GPX4 in ORes-treated breast cancer cells." (PMID 39881871, 2024). "Moreover, we found six sex-biased genes (EGFR, CDK6, PRKCB, PDCD1, KCNH2, FCGR3B, and TOP2A) in BRCA were the therapeutic targets of breast cancer." (PMID 39175079, 2024). "Established breast cancer targets CDK6 and EGFR also show high-amplitude rhythms." (PMID 38319971, 2024). "Besides, targeting the EGFR involved in EMT with the EGFR inhibitor gefitinib can inhibit the tamoxifen resistance, invasion and migration via downregulating Snail and Twist in breast cancer." (PMID 39092293, 2024). "Basal-like breast cancers are distinguished by a high expression of CK5, CK14, caveolin-1, caix, p63, and EGFR (epidermal growth factor receptor gene)/HER1, which focus mainly on the basal/myoepithelial cell components of the mammary gland, along with reduced expression of PR, ER, and HER2." (PMID 39456611, 2024). "The EGFR inhibitor erlotinib has been evaluated in two clinical trials, but was determined in both to not provide clinical benefit to breast cancer patients, even when incorporating knowledge of EGFR expression levels in the primary tumor." (PMID 38935814, 2024).
breast carcinoma (continued). "This led to the development and evaluation of drugs like trastuzumab, which targeted the HER2 protein in breast cancer cells, and lapatinib, which was a tyrosine kinase inhibitor that could target both HER2 and EGFR proteins." (PMID 38894873, 2024). "In contrast to TSL, which induces catastrophic macropinocytosis (methuosis) leading to cell death in ER+, HER2+/EGFR+ breast cancer cell lines, no cytoplasmic vacuoles were observed in NTSL-treated cells (data not shown)." (PMID 39906392, 2024). "Furthermore, efavirenz-inhibited LINE-1 action lowers the levels of recognized cancer genes in breast cancer, such as EGFR (epidermal growth factor receptor) and ERBB4 (erb-B2 receptor tyrosine kinase 4)." (PMID 39323697, 2024). "CDC42 and c-CBL are the critical components involved in the regulation of EGFR protein levels, and restoring proper EGFR degradation by disrupting the regulation of c-CBL by CDC42 can effectively reduce the proliferation and migration of breast cancer cells." (PMID 39130630, 2024). "Patients in stages 3 and 4 of breast cancer subtypes such as Her2, Luminal A, and Luminal B who test positive for CCND1, CTSD, EGFR, BCL2, and ESR1 gene expression might benefit in this regard." (PMID 39202273, 2024). "As models of EGFR+/PDGFRβ− cell lines, we used breast cancer BT-474 and epidermoid carcinoma A431 cell lines, which express moderate and high levels of EGFR, respectively, without expressing PDGFRβ, and are thus recognized by CL4 but not Gint4.T." (PMID 38532439, 2024). "In contrast, only NKAB-EGFR displayed binding to MDA-MB468 breast carcinoma cells, which highly overexpress EGFR but are negative for ErbB2." (PMID 38334638, 2024). "In a series of studies based on breast cancer cells, ICT reduced the expression of ER- α36, a key protein responsible for the development of triple-negative breast cancer (TNBC), as well as the expression of epidermal growth factor receptor (EGFR)." (PMID 39323630, 2024). "Two members of the ERBB family, EGFR and HER2, were reported to sustain HIF2α expression in breast cancer, but the underlying mechanisms were not clear." (PMID 39406703, 2024). "Furthermore, we test oncogene-targeted TKIs with EGFR, HER2, and BRAF inhibitors using EGFR-mutant (EGFR+) NSCLC, HER2-amplified (HER2+) breast cancer (BC), and BRAF-mutant (BRAF+) melanoma cells." (PMID 37880373, 2023). "Moreover, genetically engineered CAR-T cells have been developed targeting commonly expressed breast cancer antigens such as HER2, EGFR, EpCAM, AXL and c-MET." (PMID 36910138, 2023). "We have previously shown that SDC1 expression affects cancer stem cell-related pathway components, including IL-6/STAT3, Notch, and EGFR signaling pathways, in SUM-149 triple-negative inflammatory breast cancer cells, an aggressive and deadly form of breast cancer." (PMID 36980680, 2023). "It has also been revealed that EGF/EGFR could phosphorylate ER (ser118 and 167) and initiate downstream MAPK signaling in breast cancer cells, as well as STAT5b and PRLR transcription." (PMID 37415164, 2023). "NF1 loss-of-function mutations, RTKs mutations such as ERBB2 activating mutations, as well as alterations in other MAPK pathway genes (EGFR, KRAS, BRAF, and MAP2K1) were found to be enriched in endocrine-resistant advanced ER+ breast cancer compared to early-stage ER+ breast cancer." (PMID 38003387, 2023). "Next, we hypothesized that secretory proteins could act as intermediators to regulate the proliferation and invasiveness of EGFR- and HER2-positive breast cancer." (PMID 36674955, 2023).
breast carcinoma (continued). "Finally, we identified several potential therapeutic drugs for breast cancer patients in high-ACI group through CMap, including Palbociclib targeting CDK4/6 and Lapatinib targeting EGFR." (PMID 37469408, 2023). "Furthermore, a previous study demonstrated the miR-182-5p regulation on CMTM7 in breast cancer, demonstrating that EVs-miR-182-5p promoted tumor progression by regulating the CMTM7/EGFR/AKT signaling axis." (PMID 36829181, 2023). "c-Myc, EGFR signaling, and the activated PI3K pathway all promote breast cancer aerobic glycolysis, suggesting the roles of these pathways in the metabolic type of these breast cancer subtypes." (PMID 37444501, 2023). "The expression of SCUBE2 predicts a favorable outcome in epidermal growth factor receptor (EGFR)-negative and estrogen receptor (ER)α-positive breast cancers." (PMID 37237303, 2023). "For example, in metastatic and therapeutic-resistant breast cancer patient samples, EGFR/HER1 is not restricted to the cell surface, but instead can be found intracellularly in both endocytic organelles and the nucleus." (PMID 36253541, 2023). "GPER on a breast cancer-derived EnC line, for example, suggested that aldosterone does not bind to GPER; however, it does induce a direct interaction between MR and GPER and between GPER and epidermal growth factor receptor (EGFR)." (PMID 37371584, 2023). "In head and neck and esophageal squamous cell carcinomas, AXL dimerizes with EGFR and activates PKC through PLCγ, and in breast cancer pharmacological inhibition, PKC resulted in decreased AXL expression, suggesting a feedback loop between AXL expression and PKC activation." (PMID 36835239, 2023). "Moreover, CDDO-Im was shown to effectively block the EGFR/signal transducer and activator of transcription 3 (STAT3)/Sox-2 signaling pathway and consequently metastasis of breast cancer." (PMID 36982173, 2023). "Compound S62, which does not individually bind to Peli1 or EGFR, can block both linkages and shows promise for treating breast cancer with combined targeting of Peli1 and EGFR." (PMID 38179042, 2023). "GREM1-mediated EGFR activation was suggested to enhance the promoter activity of estrogen-related receptor alpha (ERRα), which is predicted to bind to the GREM1 promoter to increase GREM1 expression and drive breast cancer cell proliferation." (PMID 37615860, 2023). "The identification of myoferlin as a key regulator of EGFR (Epidermal Growth Factor Receptor) activity through inhibition of non-clathrin endocytosis in breast cancer cells was important in understanding the molecular mechanisms involved in cancer growth." (PMID 37538852, 2023). "CDK4/6 inhibitors, like palbociclib, abemaciclib, and ribociclib, EGFR inhibitors such as gefitinib and erlotinib and HER2-targeting small-molecule kinases like neratinib and tucatinib are some examples that have shown potential in treating breast cancer." (PMID 37711177, 2023). "Interestingly, the breast cancer cell lines MDA-MB-231 and T47D (which have been previously characterized as resistant to the EGFR-specific TKI erlotinib) were sensitive to cSNX1.3." (PMID 36253541, 2023). "Moreover, miR-200b restrains TNBC migration and metastasis through various mechanisms involving inactivation of EGFR and the downstream PI3K/Akt signaling pathway and suppresses FUT4 expression in cultured breast cancer cell lines." (PMID 37296801, 2023). "In breast cancer, IL-17E was synergized with EGF and conferred resistance to EGFR-TKIs." (PMID 37444399, 2023). "Similarly, Lapatinib, a dual inhibitor for EGFR/HER2 receptors, has been shown to induce apoptosis in HER2-overexpressing breast cancer cells." (PMID 37873791, 2023). "Given that EGFR is closely related to the tumorigenesis, we analyzed the PELI1 and EGFR expression using the GEPIA database, and found that PELI1 was positively correlated with EGFR expression in multiple cancers besides breast cancers." (PMID 36841821, 2023).
breast carcinoma (continued). "Additionally, WBP2 (WW domain-binding protein 2) is an emerging oncogene involved in Wnt, EGFR, Hippo, and PI3K /Akt pathways.It was reported that inhibition of WBP2 expression by miR-613 repressed breast cancer growth." (PMID 39698025, 2023). "In addition, combined with the oestrogen receptor (ER), the progesterone receptor (PR), Ki-67, CK5/6, and the epidermal growth factor receptor (EGFR), HER2 plays an important role in the molecular classification of breast cancer." (PMID 37328516, 2023). "In this section, we aim to critically investigate the role of DVL2 depletion in regulating key proteins of EGFR signaling cascade with or without HER2 inhibition in two different in vitro models of HER2+ breast cancer." (PMID 36809986, 2023). "These included olfactory transduction, primary immunodeficiency, PI3K-AKT signaling, tyrosine metabolism, chemokine signaling, JAK-STAT signaling, basal cell carcinoma, T-cell receptor signaling, Wnt signaling, EGFR tyrosine inhibitor resistance, RAS signaling, and breast cancer signaling." (PMID 37377606, 2023). "Several phase II clinical trials using an EGFR inhibitor (gefitinib or erlotinib) as monotherapy on advanced breast cancers (not necessarily TNBC) found minimal benefits from treatment, reporting PR rates of 0–3% and no reported CRs." (PMID 37627272, 2023). "However, it is currently unclear why breast cancer patients with the expression of both EGFR and HER2 have a poorer prognosis than those with the expression of EGFR or HER2 alone." (PMID 36674955, 2023). "Also, the effect of survivin siRNA-loaded EVs was confirmed in prostate cancer xenografts, orthotopic breast cancer models, and patient-derived colorectal cancer xenografts, with PSMA aptamer, EGFR aptamer, and folate-surface modification, respectively." (PMID 37717008, 2023). "Dronedarone, a multi-ion channel inhibitor, and afatinib, an EGFR inhibitor, have been studied in breast cancer previously but not in combination with BYL-719." (PMID 36900375, 2023). "However, miR-200a-5p has the opposite effect in breast cancers as suppresses cell proliferation by regulating the expression of hepatocyte growth factor (MET) and epidermal growth factor receptor (EGFR)." (PMID 36991314, 2023). "In brief, the averaged copy number of PR, EGFR or Ki67 in MDA-MB-231 is higher than that in MCF-7 or MCF-10A, possibly implying that these gene might be related to the breast cancer metastasis." (PMID 36478047, 2023). "Previous research has revealed that ubiquitin-specific protease 43 (USP43) can greatly influence breast cancer growth and metastasis by regulating EGFR/PI3K/AKT and that USP43 can also regulate the breast cancer cell cycle and epithelial–mesenchymal transition pathway, hence promoting tumorigenesis." (PMID 37050932, 2023). "Given the high therapeutic relevance of EGFR-related pathways and the lack of understanding regarding the interplay of miR-218 and EGFR in breast cancer, we aimed to determine the relation between miR-218, EGFR and therapy resistance in breast cancer." (PMID 37088795, 2023). "A dual EGFR/HER2 RTKi, effective in HER2+ breast cancer, was however ineffective in TNBC." (PMID 37190133, 2023). "Nevertheless, similar to our results presented here for colorectal cancer, we found that key genes of major cell-signaling cascades that drive tumorigenesis, e.g., JAK STAT (IL6), Src, RTK (EGFR), PI3K, and MAPK, were also highly correlated with the expression of inflammatory genes in breast cancer." (PMID 37190308, 2023). "MiR-146a, known for its tumor suppressor function through binding to the 3’ UTRs of EGFR and NOTCH1 mRNA in breast cancer and glioma, was found to present lower levels in HPV+ PC cases compared to those in HPV− PC cases, and to correlate with an expected elevation of EGFR expression." (PMID 38069131, 2023).
breast carcinoma (continued). "Treatment with THZ531 reduced the EGFR protein levels and sensitized HGSOC cells and PDOs to treatment with Lapatinib, a chemical inhibitor of the EGFR kinase activity currently in use for HER2-amplified breast cancer." (PMID 37202753, 2023). "Interaction with EGFR results in the stabilization of this EGFR–RON complex during times of cellular stress, possibly resulting in the prevention of cell cycle arrest via c-Abl in both HNSCC and breast carcinomas." (PMID 35454943, 2022). "Taken together, these observations show that EGFR clusters comprise a mixture of EGFR and HER2, to be compared with indirect findings of heterodimer formation in SKBR3 breast cancer cells from correlative fluorescence microscopy and liquid phase electron microscopy." (PMID 35612280, 2022). "Further, the public data from the Kaplan–Meier plotter indicate that high gene expression of EGFR, mTOR, MAPK, and ERK1/2 is positively associated with shorter relapse−free survival (RFS) in ER−negative breast cancer patients." (PMID 36232636, 2022). "Notably, another study revealed that AP-2γ regulated epidermal growth factor receptor and receptor tyrosine kinase (RET) expressions mediate the response to vandetanib in luminal breast cancer." (PMID 36197225, 2022). "Therefore, these “EGFR stabilizers”, including STAP-2, are good targets for the treatment of EGFR-overactivated cancers such as nonsmall cell lung, prostate, and breast cancers." (PMID 36410436, 2022). "In breast cancer, BCAP31 could foster BC cell aggressive behaviors by binding with EGFR and in turn promoting downstream pathways." (PMID 35342421, 2022). "The major chemotherapeutic drugs used nowadays to suppress breast cancer cells are developed for targeted delivery of chemo-agents against several molecular and cellular signaling pathway proteins, mainly, for example, ER, PR, HER2, VEGFR1, VEGFR2, and EGFR." (PMID 36741891, 2022). "The lack of measurable EGFR downstream phosphorylation was similar to that observed in breast cancer cells." (PMID 35054855, 2022). "Another way to inhibit kinases is the use of kinase-targeted antibodies, which has been reported to be effective in various cancers, for instance, monoclonal antibody against epidermal growth factor receptor (EGFR) in colorectal cancer and against HER2 in breast cancer." (PMID 35335890, 2022). "The anti-EGFR siRNA-loaded PEG-SSNs exerted a significant inhibitory effect on tumour development in the murine breast cancer model without any significant toxicity to healthy tissues." (PMID 36412852, 2022). "OT/OTR and EGF/EGFR signalling both play critical roles during mammary gland development, and OTR signalling often overlaps with EGFR pathways, supporting the possibility of interactions of OTR and EGFR signalling in breast cancer too." (PMID 35884900, 2022). "Inflammatory and triple-negative breast cancer (TNBC), the most aggressive forms of breast cancer are known to over-express EGFR." (PMID 35399416, 2022). "The basal breast cancer subtype is characterized by triple negativity (for ESR1, PgR and HER‐2), expression of EGFR and cytokeratin 5/6 and is a more aggressive subtype; associated with high tumour grade, younger age and poor prognosis, including shorter disease‐free and overall survival." (PMID 35579852, 2022). "In the present study, we were interested in the effects of SA in ER-positive (MCF-7) and -negative (MDA-MB-231 and BT-20) breast cancer cells in connection with the activation of EGFR expression and the AKT/mTOR pathway." (PMID 35053341, 2022). "Graviola decreased estrogen receptor (EGFR) expression, tumor marker (CA15-3) antigenicity, ROS production and lipid peroxidation, but promoted apoptosis in 7,12-dimethylbenz[a]anthracene (DMBA)-induced breast cancer in vivo." (PMID 36700235, 2022). "A negative correlation between EGFR and ER−α has been reported in many studies, and EGFR is frequently overexpressed in ER−negative breast cancer cell lines." (PMID 36232636, 2022).